YWHAG (tyrosine 3-monooxygenase/tryptophan 5-monooxygenase activation protein gamma)
Description:
Adapter protein implicated in the regulation of a large spectrum of both general and specialized signaling pathways. Binds to a large number of partners, usually by recognition of a phosphoserine or phosphothreonine motif. Binding generally results in the modulation of the activity of the binding partner. Promotes inactivation of WDR24 component of the GATOR2 complex by binding to phosphorylated WDR24. Participates in the positive regulation of NMDA glutamate receptor activity by promoting the L-glutamate secretion through interaction with BEST1. Reduces keratinocyte intercellular adhesion, via interacting with PKP1 and sequestering it in the cytoplasm, thereby reducing its incorporation into desmosomes. Plays a role in mitochondrial protein catabolic process (also named MALM) that promotes the degradation of damaged proteins inside mitochondria.
Synonyms: PPP1R170; 14-3-3GAMMA; 14-3-3γ; DEE56; EIEE56
Tractability: Small molecule: a structure with a bound ligand is known; it has a binding pocket of medium quality; it belongs to a druggable protein family. PROTAC: ubiquitination databases record sites on it; its protein half-life has been measured; a small molecule that binds it is known.
Gene: Protein-coding gene on chromosome 7 (76,326,799 to 76,358,991, reverse strand). Ensembl gene ENSG00000170027.
Subcellular location: Cytoplasm, cytosol; Mitochondrion matrix
Subcellular location (Human Protein Atlas): Cytosol; Vesicles
Pathways (Reactome):
Cell Cycle: AURKA Activation by TPX2; Chk1/Chk2(Cds1) mediated inactivation of Cyclin B:Cdk1 complex; Loss of Nlp from mitotic centrosomes; Loss of proteins required for interphase microtubule organization from the centrosome; Recruitment of NuMA to mitotic centrosomes; Recruitment of mitotic centrosome proteins and complexes; Regulation of PLK1 Activity at G2/M Transition
Disease: SARS-CoV-1 targets host intracellular signalling and regulatory pathways; SARS-CoV-2 targets host intracellular signalling and regulatory pathways
Gene expression (Transcription): Regulation of localization of FOXO transcription factors
Developmental Biology: Transcriptional and post-translational regulation of MITF-M expression and activity
Immune System: SPOP-mediated proteasomal degradation of PD-L1(CD274)
Organelle biogenesis and maintenance: Anchoring of the basal body to the plasma membrane
Programmed Cell Death: Activation of BAD and translocation to mitochondria
Signal Transduction: RHO GTPases activate PKNs
Vesicle-mediated transport: Translocation of SLC2A4 (GLUT4) to the plasma membrane
Gene Ontology:
Molecular function: identical protein binding; insulin-like growth factor receptor binding; phosphorylation-dependent protein binding; protein binding; protein kinase C binding; protein sequestering activity; RNA binding; protein kinase C inhibitor activity; protein domain specific binding; receptor tyrosine kinase binding
Biological process: cellular response to glucose starvation; negative regulation of TORC1 signaling; positive regulation of cell-cell adhesion; positive regulation of T cell activation; positive regulation of T cell mediated immune response to tumor cell; regulation of neuron differentiation; regulation of protein localization; regulation of synaptic plasticity; intracellular protein localization; negative regulation of protein kinase activity; regulation of signal transduction; cellular response to insulin stimulus
Cellular component: cytosol; extracellular exosome; focal adhesion; membrane; mitochondrial matrix; nucleus; cytoplasm; presynapse; synapse; vesicle
Genetic constraint (gnomAD): Loss-of-function variants: 1 observed, 23.26 expected, observed/expected ratio (o/e) 0.043, 90% interval 0.014 to 0.2. The upper end of that interval is the gene's LOEUF score, 0.2, which puts it in group 1 of 6, group 1 being the genes least tolerant of losing a copy. Missense variants: 151 observed, 345.36 expected, observed/expected ratio (o/e) 0.44, 90% interval 0.38 to 0.5. Synonymous variants: 160 observed, 149.53 expected, observed/expected ratio (o/e) 1.07, 90% interval 0.94 to 1.22.
Homologues: Orthologues: chimpanzee YWHAG (100% identical), dog YWHAG (100% identical), macaque YWHAG (100% identical), mouse Ywhag (100% identical), rat Ywhag (100% identical), guinea pig YWHAG (99% identical), rabbit YWHAG (99% identical), tropical clawed frog ywhag (99% identical), zebrafish ywhag2 (96% identical), zebrafish ywhag1 (96% identical), Drosophila melanogaster 14-3-3epsilon (62% identical). Paralogues in human: YWHAH (87% identical), YWHAB (76% identical), YWHAZ (75% identical), YWHAQ (70% identical), SFN (64% identical), YWHAE (63% identical).
Diseases named in the same sentence as YWHAG in open-access papers:
YWHAG is named in the same sentence as 87 diseases in open-access papers, as found by Europe PMC text mining. Sharing a sentence is not in itself a finding about the gene and the disease. The quoted sentences say what the papers report.
lung cancer (12 papers, 2008 to 2022). A malignant neoplasm involving the lung. "Besides being the marker of exosomes, ALDOA, ENO1 and YWHAG can promote metastasis, invasion, activation and proliferation of lung cancer." (PMID 36387251, 2022). "To investigate the proportion of polyploid cells induced by 14-3-3γ overexpression, we quantitated the frequency of polyploidy in H322γ cells, a lung cancer-derived cell line transfected with an expression vector that constitutively expresses the 14-3-3γ gene (YWHAG)." (PMID 29321819, 2017). "A similar relationship between YWHAG expression and polyploidy was also found when colorectal or breast adenocarcinoma data from TCGA were analyzed in the same fashion, suggesting that the relationship between upregulation of 14-3-3γ and polyploidy is not specific to lung cancers." (PMID 29321819, 2017).
glioblastoma (11 papers, 2016 to 2024). The most malignant astrocytic tumor (WHO grade IV). "Recent work has suggested that overexpression of the YWHAG protein in uterine leiomyoma cells has been reported to cause growth retardation and induce apoptosis, and miR-217 promotes the spread and invasion of glioblastoma by inhibiting YWHAG." (PMID 35928168, 2022). "CTSD expression was highest in myeloid cells, high expression of AP1S1 was shown in glioblastoma cells, and YWHAG was mainly expressed in glioblastoma cells, oligodendrocytes, and myeloid cells, and IER3 was predominantly expressed in myeloid cells." (PMID 35892430, 2022). "In this study, the results showed that CTSD and IER3 were predominantly expressed in myeloid cells, high expression of AP1S1 was shown in glioblastoma cells, and YWHAG was mainly expressed in glioblastoma cells, oligodendrocytes, and myeloid cells." (PMID 35892430, 2022). "However, YWHAG acts as a tumor suppressor gene, and miR-217 promotes cell proliferation and invasion by targeting tumor suppressor genes in glioblastoma." (PMID 35795276, 2022). "In addition, miR-217 could target YWHAG and promote the viability, proliferation, migration, invasion and mitosis of glioblastoma cells both in vitro and in vivo." (PMID 33323543, 2020). "The associated ceRNA network revealed the possible presence of the NDUFA6-DT-miR-455-3p-YWHAH/YWHAG axis in low-grade glioma (LGG) and glioblastoma multiforme (GBM), regulating the PI3K-AKT signaling pathway and influencing glioma cell survival and apoptosis." (PMID 38674418, 2024). "However, YWHAG was not identified in our study, possibly due to the different cell types used by Aghazadeh and colleagues (MA10 mouse Leydig cells), that have a very different protein expression pattern compared to the human glioblastoma cells (U87MG) used in our study." (PMID 35522669, 2022).
breast carcinoma (10 papers, 2011 to 2023). "For example, miR-181b-3p promotes epithelial–mesenchymal transition in breast cancer cells through Snail stabilization by directly targeting YWHAG." (PMID 31888623, 2019). "As an example of combinatorial regulation by miRNA is 14-3-3γ (YWHAG), which frequent overexpression is predictive of poor patient outcome in tamoxifen-resistant breast cancer and functions by activation of the MAPK and PIK pathways." (PMID 27528030, 2016). "In breast cancer, miR-181b-3p promotes EMT of breast cancer cells by targeting YWHAG." (PMID 35795276, 2022). "It was reported that YWHAG could inhibit the death of apoptotic cells and promote cell migration in breast cancer and have clinical prognostic significance as an oncogene in advanced NSCLC." (PMID 36232605, 2022). "miR-181b-3p promotes EMT in breast cancer cells by directly targeting YWHAG." (PMID 35795276, 2022). "Our data suggest that TP63, YWHAZ, BRCA1, CCND2, YWHAG, and HIPK2 can be potential genetic markers of prognostic assessment, immune infiltration and chemotherapeutic drug sensitivity in breast cancer patients." (PMID 36673982, 2023).
non-small cell lung carcinoma (7 papers, 2011 to 2025). A group of at least three distinct histological types of lung cancer, including non-small cell squamous cell carcinoma, adenocarcinoma, and large cell carcinoma. "YWHAG (tyrosine 3-monooxygenase/tryptophan 5-monooxygenase activation protein gamma, 14–3-3γ) is a factor that has been shown to be a microRNA target in COPD by us and others, as well as in non-small cell lung cancer." (PMID 38585145, 2024). "Knockdown of YWHAG suppressed EMT and reduced the metastasis of non-small cell lung cancer." (PMID 34168120, 2021).
pancreatic cancer (7 papers, 2020 to 2025). "YWHAG, one of the 14‐3‐3 phospho‐serine/phospho‐threonine binding protein lines, promoted cell proliferation in the pancreas cancer cell lines, since expression vector‐mediated overexpression enhanced cell growth." (PMID 40022573, 2025). "In pancreatic cancer, miR‐217 was identified to work as a tumor suppressor via directly targeting YWHAG to phosphorylate RAF1 and initiate ERK signaling pathway." (PMID 37626035, 2023). "YWHAG is suggested as a potential prognostic biomarker and a sensitive therapeutic target for pancreatic cancer invasion and metastasis." (PMID 31959150, 2020). "The results showed higher expression levels of YWHAG in pancreatic cancer than in normal tissue in the TCGA cohort (P < 0.01)." (PMID 31959150, 2020). "The expression of YWHAG was found to be closely related to pancreatic cancer stage via TCGA database analysis." (PMID 31959150, 2020). "However, the role of YWHAG in pancreatic cancer progression is still unclear." (PMID 31959150, 2020). "YWHAG could be used as a prognostic indicator for pancreatic cancer." (PMID 31959150, 2020). "The results showed that YWHAG could be used as a prognostic biomarker for pancreatic cancer." (PMID 31959150, 2020). "CERS6-AS1 competitively binds miR-217 to indirectly regulate the expression of YWHAG, which interacts with RAF1 and activates the ERK signaling, thereby accelerating pancreatic cancer progression." (PMID 35927226, 2022).
epilepsy (6 papers, 2021 to 2025). A brain disorder characterized by episodes of abnormally increased neuronal discharge resulting in transient episodes of sensory or motor neurological dysfunction, or psychic dysfunction. "Mutations in YWHAG, particularly de novo missense variants, disrupt the regulatory functions of 14-3-3γ, leading to diverse epilepsy phenotypes and significant neurodevelopmental challenges." (PMID 40896335, 2025). "The YWHAG gene and 14-3-3γ protein are implicated in epilepsy-associated pathways, potentially interacting with glutamate metabolism genes (Epi4K Consortium and Epilepsy Phenome/Genome Project, 2013)." (PMID 40896335, 2025). "Mutations or dysregulation of YWHAG have been associated with intellectual disabilities, autism spectrum disorders, and a spectrum of epilepsy phenotypes, including DEEs." (PMID 40896335, 2025). "YWHAG mutations, often de novo, lead to a variety of epilepsy phenotypes, from febrile seizures to severe epileptic encephalopathies." (PMID 40896335, 2025). "In conclusion, our study indicates that YWHAG mutations cause mild epilepsy, including childhood myoclonic epilepsy and FS." (PMID 33767733, 2021). "The spectrum of epilepsy caused by YWHAG mutations potentially range from mild myoclonic epilepsy and FS to severe EE." (PMID 33767733, 2021). "Furthermore, deletion of the YWHAG gene encoding 14-3-3γ is also associated with epilepsy and autistic traits in patients with atypical Williams Beuren syndrome due to deletions in 7q11.23 locus." (PMID 35602601, 2022). "Therefore, the spectrum of epilepsy caused by YWHAG mutations potentially range from mild myoclonic epilepsy and FS to severe EE." (PMID 33767733, 2021). "The exact clinical proportion of de novo versus inherited YWHAG mutation cases is unknown, although recent cohort data suggest that the vast majority, up to 86.7%, are de novo, as reported in a study of 15 individuals with YWHAG-related epilepsy." (PMID 40896335, 2025). "It is unknown whether YWHAG mutations are associated with other phenotypes of epilepsy." (PMID 33767733, 2021). "Lastly, an additional study further characterized the phenotypic spectrum of YWHAG-related epilepsy by analyzing 15 individuals from a Chinese cohort alongside 40 previously published cases." (PMID 40896335, 2025). "We examined 14-3-3 gamma (YWHAG), a protein emerging in GWAS and proteomic studies related to both AD and epilepsy." (PMID 40890882, 2025). "Further studies are required to explore the downstream protein of YWHAG that are involved in epilepsy." (PMID 33767733, 2021). "Better understanding of the roles of HIP1 and YWHAG may eventually offer avenues for rational drug design, including antiseizure agents, in these patients who often present with drug-resistant epilepsy." (PMID 35481155, 2022). "Therefore, TH alone could not explain the pathogenicity of YWHAG mutations in epilepsy." (PMID 33767733, 2021).
Parkinson disease (6 papers, 2016 to 2025). A progressive degenerative disorder of the central nervous system characterized by loss of dopamine producing neurons in the substantia nigra and the presence of Lewy bodies in the substantia nigra and locus coeruleus. "Other DMPs found were within the genes HLA-DRB5 or YWHAG, which have also been identified as risk factors in the development of FTD and Parkinson’s disease, respectively." (PMID 38791483, 2024).
gastric cancer (5 papers, 2021 to 2023). A primary or metastatic malignant neoplasm involving the stomach. "Of note, YWHAG has been shown upregulated and promoting gastric cancer progression through EMT, and the YWHAG inhibitor curcumenol in combination with cisplatin has been recently proposed as a therapeutic strategy in gastric cancer." (PMID 37369946, 2023). "The expression levels of YWHAG genes were higher in all gastric cancer tissues than in the paracancerous tissues, suggesting a poor prognosis for gastric cancer patients." (PMID 36705386, 2023). "YWHAG promoted gastric cancer proliferation and metastasis and inhibited cell apoptosis by activating Ras signaling to enhance Cyclin D1 and inhibit p21 and p27, which are key proteins in G1 of the cell cycle." (PMID 34168120, 2021). "The expression of YWHAG was remarkably overexpressed in gastric cancer, and YWHAG upregulation indicated an unfavorable prognosis." (PMID 34168120, 2021). "Researchers have found that YWHAG was significantly overexpressed in GBM, head, and neck squamous cell carcinoma, and breast and gastric cancer." (PMID 35892430, 2022).
brain ischemia (4 papers, 2021 to 2023). Diminished or absent blood supply to the brain caused by obstruction (thrombosis or embolism) of an artery resulting in neurologic damage. "Studies have shown that long-chain noncoding RNA NORAD has a protective effect on brain injury and inflammation induced by cerebral ischemia/reperfusion injury by regulating miR-30a-5p/YWHAG." (PMID 36276864, 2022). "In order to determine the biological role of YWHAG in cerebral ischemia/reperfusion injury, Ov-YWHAG was introduced to upregulate YWHAG expression and RT-qPCR analysis was employed to check the overexpression efficiency." (PMID 34709972, 2021). "In general, lncRNA NORAD may play a vital role in cerebral ischemia/reperfusion injury by sponging miR-30a-5p to increase YWHAG expression." (PMID 34709972, 2021).
developmental and epileptic encephalopathy (4 papers, 2021 to 2025). An epilepsy associated with developmental impairment that may be due to either the underlying etiology or the superimposed epileptic activity, or both. "Starting from 2010, the first chromosomal deletions covering the gene YWHAG, and later truncating and missense mutations in YWHAG have been reported to cause a developmental epileptic encephalopathy affecting infants and children (DEE56, OMIM#617665)." (PMID 40277885, 2025). "The gene encoding this protein (YWHAG) has been associated to developmental and epileptic encephalopathy (OMIM #717665), and autistic traits have been described in affected patients." (PMID 34199759, 2021).
glioma (4 papers, 2017 to 2024). A benign or malignant brain and spinal cord tumor that arises from glial cells (astrocytes, oligodendrocytes, ependymal cells). "Recently, YWHAG/14-3-3γ was found among the prognosis-relevant DNA damage and repair signature genes in glioma cells." (PMID 39682211, 2024). "In summary, we propose the potential existence of an NDUFA6-DT-miR-3p-YWHAH/YWHAG axis regulating the PI3K-AKT signaling pathway and thereby influencing glioma development in LGG and GBM." (PMID 38674418, 2024). "Our enrichment results revealed the participation of YWHAH (14-3-3γ) and YWHAG (14-3-3η) in the PI3K-AKT and Hippo signaling pathways and cell cycle in gliomas." (PMID 38674418, 2024). "Specifically, the NDUFA6-DT-miR-455-3p-YWHAH/YWHAG axis may regulate the PI3K-Akt signaling pathway, influencing glioma development." (PMID 38674418, 2024). "We identified 20 GSC-upregulated miRNA-targeted genes associated with significantly reduced 5-year survival in GBM patients, including previously identified glioma-promoting genes HMGA2, MYO1C, RGS4, and several novel targets, such as HPCAL1, IMPDH1, and YWHAG (orange-colored genes)." (PMID 29587824, 2018).
intellectual disabilities (4 papers, 2022 to 2026). "The YWHAG gene encoding 14-3-3γ, located in the 7q11.23 chromosomal region, has emerged as a significant contributor to rare neurodevelopmental disorders, particularly those associated with epilepsy and intellectual disabilities." (PMID 40277885, 2025). "Upon further clinical investigations, YWHAG-related disorders have been found to exhibit a wide spectrum of neurodevelopmental problems, mostly characterized by early-onset epilepsy, intellectual disability, motor developmental delay, speech impairment, and behavioral problems." (PMID 40277885, 2025).